MEN1 (menin 1)
Diseases named in the same sentence as MEN1 in open-access papers (continued):
Sharing a sentence is not in itself a finding about the gene and the disease.
pituitary tumor (continued). "The prevalence of pituitary tumors in MEN1 varies according to different studies, from 10 to 76%12–14." (PMID 25210615, 2014). "The role of the MEN1 gene in the etiology of other inherited endocrine disorders, in which either parathyroid or pituitary tumors occur as an isolated endocrinopathy, has been investigated by mutational analysis." (PMID 23933118, 2014). "Conventional knockout mice have been generated to assess the direct effect of several genes linked to familial pituitary tumors such as MEN1, CDKN1B, and AIP in pituitary-tumor development." (PMID 25136513, 2014). "Both familial and sporadic pituitary tumours have been shown to harbour allelic deletion on 11q13, which is the location of the recently cloned MEN1 gene." (PMID 10389976, 1999). "The most common manifestations of MEN1 include parathyroid, pancreatic, and pituitary tumors." (PMID 41155355, 2025). "Here, we analyze the state of pituitary tumors and adrenocortical tumors in the course of MEN1." (PMID 38256138, 2024). "This variety shows that alterations at different levels of the functioning of the nervous system may be involved in the development of pituitary tumors in MEN1 patients." (PMID 38256138, 2024). "In MEN1, the presence of multiple synchronous or metachronous pituitary tumors may be discovered during pre-operative evaluation or surgery for CD, consistent with other “multiplicities” that characterize this familial tumor syndrome." (PMID 37409236, 2023). "Although rare in sporadic CD, the presence of multiple synchronous or metachronous pituitary tumors may be discovered during the course of evaluation and/or surgery for CD in patients with MEN1." (PMID 37409236, 2023). "At the time of presentation, the pituitary tumors in MEN1 patients with CD may be either macro- or microadenomas." (PMID 37409236, 2023). "Therefore, a thorough skin examination should be performed in patients with PHPT, GEP, and pituitary tumors, and the finding of cutaneous lesions raises suspicion of MEN1." (PMID 37484956, 2023). "A possible explanation may be that female Men1–/– and Men1+/– mice died earlier because they developed pituitary tumors more frequently than male mice." (PMID 36048542, 2022). "Our data showed that TS overexpression reduced survival to a greater extent in Men1–/– and Men1+/– male over female mice, suggesting that TS may enhance growth of PanNETs to a greater extent than that of pituitary tumors." (PMID 36048542, 2022). "All pituitary tumors in Men1+/- mice were later identified as prolactinomas." (PMID 35600354, 2022). "The association of pituitary tumours and PPGL may also appear due to MEN1 mutation (to date, one mixed GH/PRL macroadenoma out of four PitNETs)." (PMID 33805450, 2021). "Prior series report PHP in association with pituitary tumors in which genetic testing for MEN-1 was negative." (PMID 32311048, 2020). "Since younger patients with pituitary tumors, particularly prolactinomas, have a higher prevalence of MEN1 mutations, it might be expected that patients with clinical MEN-1 would also present with pituitary tumors at a younger age." (PMID 32311048, 2020). "Thus, genetic background is an important determinant of pituitary tumour development in Men1+/- mice." (PMID 32348957, 2020). "The prevalence of pituitary tumors in patients with MEN1 is ∼40%." (PMID 30990521, 2019). "Indeed, the monoclonal antibody G6-31 has been reported to inhibit VEGF-induced pituitary tumour growth in conventional Men1+/− mice." (PMID 26320859, 2016). "Furthermore, a significant proportion of sporadic pituitary tumors harboring deletions map to the critically deleted region of the MEN1 gene." (PMID 25663877, 2015). "The MEN1-KO pituitary tumors have similar immunoreactivity with human prolactinomas." (PMID 25870702, 2014).
pituitary tumor (continued). "Patients with MEN1-related pituitary tumors tend to have a less favorable response to these standard treatments, with normalization of pituitary hormone levels observed in only 42% of MEN1 cases, compared to a 90% success rate in patients with sporadic pituitary tumors." (PMID 39201946, 2024). "Statistical analyses did not evidence any significant difference neither between disease age of onset and MEN1 four main mutation types or mutation localization, nor in the distribution of PHPT and pituitary tumours between different MEN1 mutation types and localization." (PMID 30428914, 2018). "Mutations in the MEN1 gene lead to an inherited cancer syndrome named multiple endocrine neoplasia type 1 (MEN1, disease identifier OMIM131100) typically characterized by parathyroid, pancreatic and pituitary tumors." (PMID 34356858, 2021). "The classical triad of MEN1-related tumors was present in 17 of 54 (31%) probands, PHPT and pituitary tumors in 11 (20%) and PHPT and GEP tumors in 23 (43%)." (PMID 29036195, 2017). "We investigated 23 sporadic pituitary tumours previously shown to harbour allelic deletion on 11q13 with the marker PYGM centromeric and within 50 kb of the MEN1 locus." (PMID 10389976, 1999). "Histopathological features do not reliably distinguish between sporadic and MEN1-related pituitary tumors." (PMID 39201946, 2024). "Despite their tendency to be more invasive and less responsive to treatment, MEN1-related pituitary tumors do not show a higher incidence of malignant transformation compared to sporadic tumors." (PMID 39201946, 2024). "Others have reported the presence of multiple synchronous or metachronous pituitary tumors in MEN1 patients both with and without CD." (PMID 37409236, 2023). "Pituitary hyperplasia alone or coexisting with a pituitary tumour is more common in patients with MEN1/MEN4 compared to MEN1-negative tumours." (PMID 33805450, 2021). "In the Dutch MEN1 cohort, approximately half of the pituitary tumors including ∼50% nonfunctioning microadenomas were identified during screening." (PMID 30990521, 2019). "The analysis of our MEN1 database confirmed PHPT as the most common manifestation of the syndrome, reaching a penetrance of over 95% after the age of 55, followed by GEP-NETs (about 60%) and pituitary tumours (about 52%), respectively." (PMID 30428914, 2018). "The MEN1-KO pituitary tumors were prolactinomas and unlike non-tumoral pituitary tissue of MEN1-KO, displayed no PRL-FSH colocalization." (PMID 25870702, 2014). "Pituitary tumors MEN1 mice, one year old were immunoreactive for PRL, but not for other pituitary hormones." (PMID 25870702, 2014). "Such potential pituitary tumor multifocality must be kept in mind during preoperative tumor localization for CD in MEN1 patients, since visualized pituitary lesions may not necessarily correspond to the culprit functional corticotrope adenoma." (PMID 37409236, 2023). "The co-occurrence of parathyroid and pituitary tumors represented the hallmark of mutation-negative genotype, whereas 97% of MEN1-positive probands presented parathyroid and GEP tumors or the association of the three main MEN1-related tumors." (PMID 29036195, 2017). "Interestingly, 86% of all index cases with PHPT and pituitary tumors were MEN1 mutation-negative, whereas 69% of patients with PHPT associated with pituitary tumors and GEP-NETs were MEN1 mutation-positive." (PMID 29036195, 2017). "However, our findings suggest that let-7a does not regulate Kras in pituitary tumours of Men1+/− mice and that it may act via alternative targets." (PMID 30389902, 2018). "Indeed, gene replacement therapy using an adenoviral vector containing Men1 cDNA that was delivered directly to the pituitary tumours of Men1+/− mice, restored menin expression in the pituitary tumours and reduced their proliferation, without significant adverse effects or increased mortality." (PMID 26320859, 2016).
pituitary tumor (continued). "In conclusion, the co-occurrence of the three major MEN1-related manifestations, namely PHPT, GEP and pituitary tumors, or only parathyroid and GEP tumors, with or without the presence of minor MEN1-related manifestations, represents the best predictor of a MEN1positive test." (PMID 29036195, 2017).
adenoma (47 papers, 2010 to 2026). A neoplasm arising from the epithelium. "Only a handful of mixed ACTH-PRL secreting adenomas have been reported, two of which had genetic predisposition (MEN1 in one case and AIP mutation in another)." (PMID 41201503, 2025). "Quantitatively, centromere 11 loss and MEN1 LOH were much more frequent in the MEN1 adenoma compared to the non-MEN1 adenoma." (PMID 38244045, 2024). "MEN1 syndrome associated with PanNET displaying loss of the WT MEN1 allele is observed in 100% of cases: loss of the WT MEN1 allele is observed in micro-adenomas, thus implying that MEN1 loss is an early event." (PMID 29156578, 2017). "Two of these 59 somatic mutations (in 2 separate adenoma cases) involved the MEN1 gene, a previously established contributor to parathyroid neoplasia." (PMID 25594030, 2014). "Both mutational and LOH analyses of MEN1 allele in normal parathyroid and sporadic adenoma tissues showed homozygous wild-type MEN1 allele." (PMID 22761894, 2012). "Interestingly, the adenoma showed homozygous somatic MEN1 mutations, possibly as a consequence of the increased risk of genetic alterations in the context of this syndrome." (PMID 35743266, 2022). "Since Men1+/ΔN3-8 mice did not develop carcinoma when tested up to 21 months of age, we asked whether loss of heterozygosity (LOH) occurs in Men1+/ΔN3-8 mice that develop adenoma as well as in hTS/Men1+/ΔN3-8 mice that develop carcinoma by 9 months of age." (PMID 36048542, 2022). "The rate of GH-secreting adenomas was significantly lower (P<0.05) in MEN1-positive than in MEN1-negative patients of the cohort, whereas the rate of prolactin-secreting adenomas was significantly higher in MEN1-mutated than MEN1-negative probands and cohort (P<0.05 and P<0.01, respectively)." (PMID 29036195, 2017). "The patient was found to have adenomas in the pituitary, parathyroid, and pancreatic glands, consistent with the manifestations of MEN1." (PMID 40144450, 2025). "Surgical strategies are tailored to biomarker-defined risks: focused parathyroidectomy for localized adenomas, subtotal resection for multigland disease (e.g., MEN1 carriers), or en-bloc resection for carcinoma-predictive signatures (CDC73 mutations)." (PMID 41210508, 2025). "Following high clinical suspicion for MEN1, pituitary gland was evaluated with a laboratory workup and a targeted MRI imaging that excluded pituitary hypersecretion and/or adenomas." (PMID 38294658, 2024). "All 25/25 (100%) MEN1 adenomas showed sparse stromal fat, at least focal cystic configurations, and an absence of calcifications, necrosis, or invasion of adjacent skeletal muscles or vessel invasion." (PMID 38244045, 2024). "Focal endocrine atypia in terms of larger irregular hyperchromatic nuclei was found in 3/25 (12.0%) MEN1 adenomas." (PMID 38244045, 2024). "Even though there were many non-interpretable signals, we consistently noticed MEN1 loss of heterozygosity (LOH) and/or centromere 11 in the micronodules of the MEN1 adenoma." (PMID 38244045, 2024). "In total, 17/25 (68.0%) MEN1 adenomas showed at least one fibrous septum, and 19/25 (76.0%) adenomas were at least partially encapsulated." (PMID 38244045, 2024). "There were 17 diseased parathyroid tissues from 12 patients with primary HPT, including three patients with MEN1, eight with single adenomas, one with parathyroid cancer, and six normal parathyroid glands accompanied by diseased tissue." (PMID 37732116, 2023). "Five adenoma lobules from the same tumor section harvested from each of the Men1–/– (n = 2) and hTS/Men1–/– (n = 2) mice with adenoma were scored and compared for Ki-67 expression." (PMID 36048542, 2022). "To evaluate the role of elevated hTS in promoting tumor cell proliferation, we analyzed Ki-67 expression in adenoma and carcinoma isolated from both Men1–/– and hTS/Men1–/– mice." (PMID 36048542, 2022).
adenoma (continued). "Scheduled necropsy of pancreatic tissues isolated from hTS/Men1–/– and hTS/Men1+/ΔN3-8 mice showed that hTS overexpression accelerates hyperplasia, adenoma, and islet cell carcinoma in comparison with control Men1–/– and Men1+/ΔN3-8 mice." (PMID 36048542, 2022). "The MEN1 gene is responsible for the occurrence of multiple proliferative changes (hyperplasia, adenomas, and carcinomas)." (PMID 35807169, 2022). "We observed that 3 of 16 hTS/Men1–/– mice (18.8%) developed islet adenomas at 5 months of age while 0 of 16 of Men1–/– mice developed adenomas at this time point." (PMID 36048542, 2022). "For example, the progression to adenoma and carcinoma was pronounced at 6.5 months: 5 of 16 hTS/Men1–/– mice developed carcinoma (31.3%) as compared with 0 of 16 Men1–/– mice with carcinoma at this time point (0%)." (PMID 36048542, 2022). "Long-acting octreotide has been proposed as a possible treatment for PHPT due to adenoma in MEN1 patients." (PMID 31336364, 2019). "As has been previously observed, pancreatic endocrine pathology is frequently observed in Men1+/− animals, and in our Men1+/− animals was histologically described as adenoma, which were typically immunopositive for insulin." (PMID 22708734, 2012). "The parathyroid surgeon synthesizes these inputs to determine the extent of resection—focused parathyroidectomy for localized adenomas versus subtotal resection for multiglandular disease (e.g., MEN1 carriers)—aided by intraoperative PTH monitoring to confirm cure." (PMID 41210508, 2025). "Importantly, the majority of MEN1 adenomas (16/25 [64.0%]) in our cohorts revealed at least one distinct large nodule with up to 11 additional smaller (micro)nodules." (PMID 38244045, 2024). "Interestingly, although prolactinomas are the most common form of functioning adenoma in MEN1, in MEN4, they seem to be the rarest type, with only one case reported." (PMID 35355569, 2022). "We found a 4-fold increase in Ki-67 index in adenoma isolated from hTS/Men1–/– mice compared with adenoma from Men1–/– mice (P = 0.0006) and a 3.2-fold increase of Ki-67 index in carcinoma isolated from hTS/Men1–/– mice when compared with carcinoma from Men1–/– mice (P = 0.024)." (PMID 36048542, 2022). "H&E staining confirmed adenoma in Men1+/ΔN3-8 and carcinoma in hTS/Men1+/ΔN3-8 mice." (PMID 36048542, 2022). "Patients with FHH should avoid operative treatment, and PHPT should be differentiated from MEN1 to determine whether surgery should include parathyroidectomy with removal of one adenoma or 3.5 hyperplastic parathyroid glands." (PMID 34556169, 2021). "This inverse correlation was present only when the wild type copy of the MEN1 gene was still retained in the tumoral tissue, while in MEN1 adenomas presenting LOH at the 11q13 locus, menin resulted to be unexpressed and miR-24-1 was expressed at a very low level." (PMID 34298972, 2021). "In addition, >25% of MEN1 patients have been reported to develop thyroid tumors, including adenomas, carcinomas and colloid goiters." (PMID 25663877, 2015). "In our whole-exome sequencing, samples harboring somatic ZFX mutations did not overlap with those containing somatic mutations in MEN1, which were detected in 2 of the 19 sporadic adenomas." (PMID 25594030, 2014). "In conclusion, comparative Whole Exome Sequencing (WES) analysis of three adrenal tumors in a MEN1 patient suggests a possible relationship between malignant and benign lesions occurring in MEN1 patients, without, however, demonstrating any causal adenoma-to-carcinoma progression driven by MEN1 LOH." (PMID 41806143, 2026). "Despite no report on identified MEN1 mutations in patients with a prolactinoma and an aldosterone-producing adenoma, the rare combination of tumors might occur in the MEN1 patients." (PMID 21034446, 2010). "MEN1-related PHPT is distinguished by diffuse parathyroid hyperplasia, contrasting with the single adenomas commonly observed in sporadic PHPT." (PMID 39201946, 2024).
adenoma (continued). "The MEN1 gene product “menin” directly interacts with the vitamin D receptor (VDR) and enhances gene transcription, leading to lower VDR expression in adenoma cells." (PMID 38115826, 2023). "Cdk4 is required for ErbB-2-driven mammary tumorigenesis, DMBA/TPA-induced skin tumor development, Men1+/−-driven neuroendocrine tumorigenesis, PDGF-induced glioma and APCMin/+-driven adenoma." (PMID 33806417, 2021). "Somatotrophinomas and corticotrophinomas, along with non-functioning adenomas, constitute other anterior pituitary tumors observed in MEN1 patients, with clinical manifestations dependent on hormone secretion and tumor size." (PMID 39201946, 2024). "Up to 88-97% of MEN1 patients suffer PHPT due to parathyroid hyperplasia and/or adenoma." (PMID 37795364, 2023). "We also observed loss of p21Cip1 and p18INK4c expression in pancreatic islet tumors from both Men1–/– (n = 4; 2 adenoma and 2 carcinoma) and hTS/Men1–/– mice (n = 4; 2 adenoma and 2 carcinoma), while p27Kip1 expression was not affected." (PMID 36048542, 2022). "A single study reported the presence of MEN1 mutation in three patients from two families of their cohort, one of which had a corticotrope adenoma and none of them with other features of MEN1 syndrome, suggesting a potential role of MEN1 in AIP-WT FIPAs." (PMID 35743266, 2022). "It is reported to normalize serum calcium in 70–80% of patients with PHPT due to sporadic adenomas in cases where surgery is not an option, but data on MEN1-related PHPT are scarce." (PMID 35407574, 2022). "Conversely, miR-664 resulted to be upregulated in MEN1 non-LOH adenomas and down-regulated in MEN1 LOH adenomas, both with respect to non-MEN1 controls." (PMID 34298972, 2021). "Patient No. 8 additionally presented with left adrenal nonfunctional adenoma and was clinically suspected of having MEN1." (PMID 30522468, 2018). "Fourth, the FISH procedure led to relatively weak signals (frequently not interpretable) and could only be performed on a single MEN1 adenoma." (PMID 38244045, 2024). "In addition, we did not analyze the difference of MEN1 in adenomas, carcinomas, or sporadic tumors due to the limitation of sample size." (PMID 35879975, 2022). "A microarray profiled expression of 1890 human microRNAs (miRNAs) between MEN1 PAs with somatic MEN1 LOH (MEN1 LOH PAs) and MEN1 PAs still retaining one wild type copy of the MEN1 gene (MEN1 non-LOH PAs), showed 3 miRNAs as significantly differentially expressed between the two groups of adenomas." (PMID 34681865, 2021). "The same conclusion was recently reached also for sporadic PanNET: aberrant MEN1 expression was observed in 74% of micro-adenomas; in contrast, none of these micro-adenomas display the alternative lengthening of telomeres phenotype and do not display DAXX and ATRX loss." (PMID 29156578, 2017). "Therefore, in selected cases, such as lack of genetic preoperative diagnosis of MEN1, evidence of less than four enlarged parathyroids, and “adenoma-like” kinetics of intraoperative iPTH, they believe conservative PTX should be taken into consideration." (PMID 23259638, 2012). "However, these synchronous adenomas may also occur outside familial disease, as in our patient's case who did not have a family history consistent with MEN1 or familial isolated pituitary adenoma syndrome." (PMID 25298881, 2014). "The literature shows that prolactinomas are the most prevalent in the context of MEN1 (~65%), followed by somatotropinoma, ACTH-secreting adenoma, and non-functioning adenomas." (PMID 36967793, 2023). "miR-1301 was up-regulated in MEN1 LOH PAs with respect to both the MEN1 non-LOH PAs and sporadic non-MEN1 adenomas." (PMID 34681865, 2021).